CBX1P3 (chromobox 1 pseudogene 3)
Gene: Transcribed processed pseudogene on chromosome 1 (203,954,640 to 203,955,780, forward strand). Ensembl gene ENSG00000237379.
Diseases named in the same sentence as CBX1P3 in open-access papers:
CBX1P3 is named in the same sentence as 1 disease in open-access papers, as found by Europe PMC text mining. Sharing a sentence is not in itself a finding about the gene and the disease. The quoted sentences say what the papers report.
breast carcinoma (1 paper, 2020). "We find that increased CTSLP8 (Wald p-value = 5.0 × 10− 05), increased EEF1GP4 (Wald p-value = 1.0 × 10− 06), decreased HLA-K (Wald p-value = 8.0 × 10− 05), increased CBX1P3 (Wald p-value = 1.0 × 10− 03), and increased RPS10P20 (Wald p-value = 2.0 × 10− 03) indicate worse prognosis in breast cancer." (PMID 32241256, 2020).